NHERF2 (NHERF family PDZ scaffold protein 2)
Description:
Scaffold protein that connects plasma membrane proteins with members of the ezrin/moesin/radixin family and thereby helps to link them to the actin cytoskeleton and to regulate their surface expression. Necessary for cAMP-mediated phosphorylation and inhibition of SLC9A3. May also act as scaffold protein in the nucleus.
Synonyms: NHERF-2; SIP-1; TKA-1; SLC9A3R2; E3KARP; OCTS2; NHE3RF2; SIP1
Tractability: Antibody: UniProt places it where antibodies can reach, with high confidence; its Gene Ontology location is reachable by antibodies, with high confidence; the Human Protein Atlas places it where antibodies can reach. PROTAC: ubiquitination databases record sites on it.
Gene: Protein-coding gene on chromosome 16 (2,025,356 to 2,039,026, forward strand). Ensembl gene ENSG00000065054.
Subcellular location: Endomembrane system; Nucleus; Apical cell membrane
Subcellular location (Human Protein Atlas): Plasma membrane
Gene Ontology:
Molecular function: beta-catenin binding; cadherin binding; identical protein binding; phosphatase binding; protein binding; signaling receptor binding; protein-membrane adaptor activity; type 2 metabotropic glutamate receptor binding; type 3 metabotropic glutamate receptor binding; molecular adaptor activity
Biological process: protein localization to plasma membrane; protein-containing complex assembly
Cellular component: extracellular exosome; focal adhesion; plasma membrane; apical plasma membrane; nucleus; endomembrane system
Genetic constraint (gnomAD): Loss-of-function variants: 33 observed, 28.6 expected, observed/expected ratio (o/e) 1.15, 90% interval 0.87 to 1.54. The synonymous counts are far from expectation, so gnomAD's model fits this gene poorly and the ratio says little. Missense variants: 490 observed, 399.7 expected, observed/expected ratio (o/e) 1.23, 90% interval 1.14 to 1.32. Synonymous variants: 246 observed, 168.66 expected, observed/expected ratio (o/e) 1.46, 90% interval 1.31 to 1.62.
Homologues: Orthologues: chimpanzee NHERF2 (99% identical), macaque NHERF2 (97% identical), guinea pig NHERF2 (93% identical), mouse Nherf2 (92% identical), rat Nherf2 (89% identical), pig NHERF2 (65% identical), tropical clawed frog nherf2 (64% identical), dog NHERF2 (54% identical), Drosophila melanogaster CG10939 (26% identical). Paralogues in human: NHERF1 (51% identical), NHERF4 (32% identical), PDZK1 (31% identical).
Diseases named in the same sentence as NHERF2 in open-access papers:
NHERF2 is named in the same sentence as 23 diseases in open-access papers, as found by Europe PMC text mining. Sharing a sentence is not in itself a finding about the gene and the disease. The quoted sentences say what the papers report.
breast carcinoma (4 papers, 2014 to 2023). "Interestingly, a previous study showed that NHERF1 with a mutation in the PDZ2 domain changes its localization in breast cancer; since we have not observed a similar phenotype with NHERF2, this indicates that modifications in NHERF2 might have exclusive roles in carcinogenesis." (PMID 37623973, 2023).
colon cancer (2 papers, 2020). "LPA2 receptor signaling regulates the function of colon cancer cells and is also associated with membrane-associated guanylate kinases, including MAGI-3 and NHERF-2." (PMID 32284748, 2020). "NHERF-2 competes with MAGI-3 for binding to LPA2, which has the opposite effect on the function of the LPA2 receptor to regulate colon cancer cells." (PMID 32284748, 2020).
colorectal cancer (1 paper, 2023). A primary or metastatic malignant neoplasm that affects the colon or rectum. "To explore its function in colorectal cancer cells, we conducted experiments, which showed that NHERF2 can inhibit the malignant behaviors of colorectal cancer cells." (PMID 37573425, 2023). "We showed that SLC26A3 promoted NHERF2 interaction with IκB in colorectal cancer cells." (PMID 37573425, 2023). "Based on our results, we conclude that NHERF2 can inhibit the proliferation, migration, and metastasis of CRC cells, thereby providing new insights into the gene’s role in colorectal cancer." (PMID 37573425, 2023).
diabetic nephropathy (1 paper, 2015). "Interaction with Nherf2 and ezrin and participation in the PDGFβ signaling axis highlights the possibility of Schip1 involvement in diabetic nephropathy, which should be the course for future functional studies of this protein." (PMID 25807495, 2015).
diarrheal disease (1 paper, 2020). The condition of having at least three loose or liquid bowel movements each day. "As the regulation of LPA5 depends on its interaction with NHERF2, LPA may be useful in treating some diarrheal diseases." (PMID 32194420, 2020).
mycobacterial infection (1 paper, 2025). "Moreover, upregulation of NHERF2 was confirmed by immunoblotting of serum EVs and immunohistochemistry of lungs with mycobacterial infection." (PMID 39940923, 2025).
oropharyngeal tumors (1 paper, 2023). "In order to define these potential differences, we decided to monitor NHERF2 changes in HPV16+ and HPV− oropharyngeal tumors." (PMID 37623973, 2023).
tumor (8 papers, 2020 to 2023). "Our study data revealed that NHERF2 decreases IκB ubiquitination, which is associated with the inhibition of malignant behavior of tumor cells, such as cell proliferation, necrosis, and metastasis." (PMID 37573425, 2023). "Collectively, our findings provide compelling evidence that NHERF2 plays a vital role in CRC as a tumor suppressor by suppressing the malignant biological behaviors of CRC cells." (PMID 37573425, 2023). "And NHERF2 has also been shown that it can suppress tumor via recruit PTEN to inhibit the activation of the PI3K." (PMID 37573425, 2023). "For example, increased expression the coactivators SRC-1 and NHERF2 or the loss of expression of corepressors such as NCoR and TTP correlate with cell proliferation, tumor development and progression." (PMID 33117284, 2020). "We hypothesize that SLC26A3 plays a critical role in tumor inhibition via the SLC26A3/NHERF2-IκB/NF-κB/p65-SLC26A3 feedback loop." (PMID 37573425, 2023). "In short, a gradual decrease in NHERF2 levels accompanied the decrease in cellular differentiation of HPV− cancers, whilst the protein localization remained the same between different tumor grades." (PMID 37623973, 2023). "Subsequent evaluation showed that NHERF2 overexpression exerted inhibitory effects on CRC cell proliferation and significantly curbed tumor formation as indicated by colony formation assays." (PMID 37573425, 2023). "For example, changes in protein levels of coregulators SRC-1; NHERF2, TTP have been shown to correlate with tumor proliferation, disease recurrence or poor disease-free survival in breast cancer." (PMID 33117284, 2020). "Notably, the absence of NHERF2 in vivo decreases STAT3 activation and tumor growth, which means that NHERF2 may be a potential target for cancer treatment." (PMID 36286020, 2022).
cancer (5 papers, 2013 to 2023). A tumor composed of atypical neoplastic, often pleomorphic cells that invade other tissues. "More interestingly, loss of NHERF2 appears to lead to p27 downregulation, which is a hallmark of many cancers." (PMID 37623973, 2023). "Prior to studying NHERF2 expression patterns in cancer samples, its expression and localization were investigated in healthy, uninfected tonsillar tissue." (PMID 37623973, 2023). "We also showed a significant decrease in NHERF2 immunoreactive cancer cells in HPV16+ samples suggesting its importance in HPV-driven oropharyngeal carcinogenesis." (PMID 37623973, 2023). "Greater variation was detected in the presence of HPV16, so this difference between the control tissue and HPV16+ OPSCCs was significant with a p-value of 0.0013, indicating that the presence of HPV16 E6 in these cancer types reduced the amount of NHERF2." (PMID 37623973, 2023). "In addition to a decrease in its protein level, we also observed a decrease in NHERF2 index or percentage of immunoreactive cancer cells with the higher grade of HPV− OPSCCs, but this was even more pronounced in the presence of HPV16." (PMID 37623973, 2023). "NHERF2 protein was localized exclusively in the cytoplasm in these cancer cells." (PMID 37623973, 2023). "In G1 OPSCC, NHERF2 was detected in all samples predominantly as high-intensity staining (4/7 samples), similar to that observed in the control samples, and it was mostly accompanied by a large proportion of immunoreactive cancer cells." (PMID 37623973, 2023). "Interestingly, although G3 HPV− OPSCCs are morphologically similar to HPV16+ OPSCCs, with both cancer types exhibiting poorly differentiated to undifferentiated phenotypes, the decrease in NHERF2 expression was even more evident in the presence of HPV16." (PMID 37623973, 2023). "Furthermore, we observed a significant reduction in the percentage of NHERF2 immunoreactive cancer cells in HPV16+ tumors, compared with well and moderately differentiated HPV− OPSCCs, suggesting the importance of 16E6’s targeting of NHERF2 in HPV-driven oncogenesis in the head and neck area." (PMID 37623973, 2023). "Knockdown of MAGI3 increases expression of NHERF-2, which enhances cell growth, COX-2 expression and ensures cancer resistance to chemotherapy." (PMID 23844591, 2013). "Together with our new results it raises the question whether NHERF2, as a modulator of ERM phosphorylation via ROCK2, may affect invasiveness of carcinoma cells." (PMID 24364877, 2013).
infection (2 papers, 2010 to 2015). The state of being infected such as from the introduction of a foreign agent such as serum, vaccine, antigenic substance or organism. "Indeed, during infection of mice with wild-type C. rodentium NHERF2 was extensively recruited to the bacterial attachment sites (data not shown)." (PMID 20618342, 2010).
NHERF2 also shares sentences with these, for which no sentence is quoted: cystic fibrosis (2 papers); lung carcinoma (2); Arthritis (1); deafness (1); fibrosarcoma (1); Hypertension (1); nephrosis (1); nephrotic syndrome (1); Oropharyngeal Cancers (1); osteoporosis (1); Pulmonary Disease (1); tuberculosis (1); Usher syndrome (1).